TFPI2 (tissue factor pathway inhibitor 2)
Description:
May play a role in the regulation of plasmin-mediated matrix remodeling. Inhibits trypsin, plasmin, factor VIIa/tissue factor and weakly factor Xa. Has no effect on thrombin.
Synonyms: TFPI-2; PP5; REF1
Tractability: Antibody: its Gene Ontology location is reachable by antibodies, with high confidence; UniProt places it where antibodies can reach, with medium confidence; UniProt predicts a signal peptide or a membrane-spanning region.
Gene: Protein-coding gene on chromosome 7 (93,885,396 to 93,890,753, reverse strand). Ensembl gene ENSG00000105825.
Subcellular location: Secreted
Pathways (Reactome):
Developmental Biology: Developmental Lineage of Pancreatic Ductal Cells
Gene Ontology:
Molecular function: extracellular matrix structural constituent; serine-type endopeptidase inhibitor activity; peptidase inhibitor activity
Cellular component: extracellular matrix; extracellular region
Genetic constraint (gnomAD): Loss-of-function variants: 22 observed, 23.5 expected, observed/expected ratio (o/e) 0.94, 90% interval 0.67 to 1.34. The upper end of that interval is the gene's LOEUF score, 1.34, which puts it in group 5 of 6, group 1 being the genes least tolerant of losing a copy. Missense variants: 289 observed, 304.06 expected, observed/expected ratio (o/e) 0.95, 90% interval 0.86 to 1.05. Synonymous variants: 119 observed, 115.36 expected, observed/expected ratio (o/e) 1.03, 90% interval 0.89 to 1.2.
Homologues: Orthologues: chimpanzee TFPI2 (99% identical), macaque TFPI2 (93% identical), pig TFPI2 (74% identical), dog TFPI2 (71% identical), guinea pig TFPI2 (61% identical), mouse Tfpi2 (52% identical), tropical clawed frog tfpi2 (46% identical), rat Tfpi2 (44% identical), zebrafish tfpi2 (37% identical), Caenorhabditis elegans K12G11.6 (19% identical), Caenorhabditis elegans C02F12.5 (17% identical), Caenorhabditis elegans Y55F3BR.2 (16% identical), and 1 more. Paralogues in human: TFPI (34% identical), SPINT1 (29% identical), AMBP (23% identical), WFIKKN1 (23% identical), WFIKKN2 (23% identical), KIAA0319L (20% identical), SPINT2 (19% identical), KIAA0319 (17% identical), WFDC8 (17% identical), EPPIN (13% identical), SPINT4 (12% identical), LRP11 (10% identical), and 1 more.
Diseases named in the same sentence as TFPI2 in open-access papers:
TFPI2 is named in the same sentence as 122 diseases in open-access papers, as found by Europe PMC text mining. Sharing a sentence is not in itself a finding about the gene and the disease. The quoted sentences say what the papers report.
breast cancer (26 papers, 2007 to 2025). A primary or metastatic malignant neoplasm involving the breast. "In conclusion, this research has adeptly uncovered pivotal roles that CYP24A1 and TFPI2 undertake in breast cancer, and has established a predictively precise risk assessment model." (PMID 39068476, 2024). "This research aimed to elucidate the roles of CYP24A1 and TFPI2 genes in breast cancer and to formulate a predictive model for risk assessment with robust characteristics." (PMID 39068476, 2024). "Concurrently, while TFPI2 has previously been associated with tumor genesis and prognosis in various cancers, its exact role and prognostic value in breast cancer have largely remained underexplored." (PMID 39068476, 2024). "In conclusion, TFPI-2 mRNA levels were upregulated by miR-494 in MCF-7 breast cancer cells most likely by an indirect association where miR-494 targeted the transcription factors AHR and ELF-1." (PMID 32132611, 2020). "Down-regulation of TFPI2 was found to be associated with poor survival in patients with breast cancer." (PMID 32248791, 2020). "The underlying mechanism involved in regulation of breast cancer progression via TFPI2-mediated TWIST1 was then determined." (PMID 32248791, 2020). "Mechanistically, Twist-related protein 1 (TWIST1) was negatively associated with TFPI2 in breast cancer patients, whose expression was decreased by TFPI2 over-expression or increased by TFPI2 knockdown." (PMID 32248791, 2020). "Tissue factor pathway inhibitor 2 (TFPI2) participates in carcinogenesis of various tumors, and is associated with poor survival of breast cancer patients." (PMID 32248791, 2020). "TFPI2 was down-regulated in breast cancer tissues and cell lines, and was associated with poor prognosis of patients diagnosed with breast cancer." (PMID 32248791, 2020). "For paclitaxel we found that three genes were reported to be associated with ovarian cancer (HOXB2, MYC, and TFPI2; p=0.024) and two genes were strongly associated with tumorigenesis of breast cancer (DUSP2 and ITGA3; p<0.001)." (PMID 29416679, 2018). "In this study, we investigated the mechanisms underlying the invasion-suppressive effect of TFPI-2 in breast cancer cells." (PMID 29051606, 2017). "More importantly, TFPI-2 expression was also associated with disease-free survival (DFS) of breast cancer patients." (PMID 23497249, 2013). "We cloned the potential promoter region (from-1 436 to +75) of TFPI-2 gene and found several genetic mutations among breast cancer cell lines." (PMID 18053161, 2007). "Previous work suggested that TFPI2 could cause decreased invasiveness and/or proliferation of gliomas, glioblastoma, breast cancer, and melanomas." (PMID 34249699, 2021). "However, the effect and underlying mechanism of TFPI2 on breast cancer progression remains to be investigated." (PMID 32248791, 2020). "Lower TFPI-2 expression is associated with breast cancer progression, recurrence and poor survival." (PMID 29051606, 2017). "Therefore, the regulatory mechanism of TFPI2 in breast cancer progression might be associated with TWIST1 expression." (PMID 32248791, 2020). "Moreover, we found that the hazard ratio (Exp(B)) of DFS is 0.316 (P <0.01), indicating that the group with lower TFPI-2 expression may have about 3 times more risk of breast cancer relapse." (PMID 23497249, 2013). "Estradiol induces TFPI2 expression via estrogen receptor α (ERα) activation in MCF7 breast cancer cells." (PMID 40361374, 2025). "Immunohistochemical analysis has identified TFPI2-positive and TFPI2-negative cell populations in malignancies like G3 breast cancer, gastric cancer, colorectal cancer, endometrial cancer, and ovarian cancer." (PMID 40361374, 2025). "Overexpression of TFPI-2 in breast cancer cell lines (e.g., MCF7, T47D) led to decreased phosphorylation of ERK1/2 proteins." (PMID 40361374, 2025). "Overexpression or recombinant TFPI2 suppresses breast cancer cell growth and invasion, reinforcing its role as a tumor suppressor." (PMID 40361374, 2025).
breast cancer (continued). "In breast cancer, miR-494 indirectly downregulates TFPI2 by modulating E74-like factor 1 (ELF-1) and aryl hydrocarbon receptor (AHR), promoting tumor growth." (PMID 40361374, 2025). "This will help validate the prognostic relevance of CYP24A1 and TFPI2 in a more diverse range of breast cancer cases, thus enhancing the generalizability and clinical utility of our findings." (PMID 39068476, 2024). "Survival analysis was performed using Kaplan-Meier curves, and the results revealed a significant correlation between CYP24A1 and TFPI2 with the prognosis survival time of breast cancer patients." (PMID 39068476, 2024). "This study endeavors to shed light on this association, establishing a foundational platform for subsequent studies concerning TFPI2 and breast cancer." (PMID 39068476, 2024). "Validation of the GEO dataset revealed a significant correlation between the expression of CYP24A1 and TFPI2 genes and the survival status of breast cancer patients." (PMID 39068476, 2024). "Further scientific exploration into the biological mechanics regulated by CYP24A1 and TFPI2 is imperative, focusing particularly on their impact on breast cancer cell proliferation, metastasis, and therapeutic responsiveness." (PMID 39068476, 2024). "To further investigate the effects of CYP24A1 and TFPI2 on the tumorigenic capacity of breast cancer cells in vivo, we established a nude mouse xenograft animal model for breast cancer transplantation." (PMID 39068476, 2024). "Both TFPI-2 overexpression and exogenous rTFPI-2 (recombinant TFPI-2) inhibited proliferation and invasion of breast cancer cells." (PMID 39153052, 2024). "TFPI-2 is frequently downregulated in the vast majority of aggressive tumors such as glioma, breast cancer, melanoma, colorectal cancer, and pancreatic cancer, just to name a few." (PMID 36900315, 2023). "Differential regulation of TFPI-2 has been found in a variety of diseases, including breast cancer, where it has been shown to have a role in tumor suppression." (PMID 32132611, 2020). "The present study for the first time indicated that TFPI2 suppressed breast cancer progression through inhibiting TWIST-integrin α5 pathway." (PMID 32248791, 2020). "TFPI2 suppressed breast cancer progression through inhibiting TWIST-integrin α5 pathway, providing a new potential therapeutic target for breast cancer treatment." (PMID 32248791, 2020). "As a common Kunitz serine protease inhibitors TFPI2 is involved in various tumor progression, especially in breast cancer." (PMID 32248791, 2020). "The expression level of TFPI2 in breast cancer tissues and cell lines was examined via qRT-PCR (quantitative real-time polymerase chain reaction) and immunohistochemistry." (PMID 32248791, 2020). "In this study we aimed to explore if miR-494 is involved in the regulation of TFPI-2 in breast cancer cells using the breast cancer cell line MCF-7." (PMID 32132611, 2020). "Since TWIST1 has been reported to be involved in progression of breast cancer, the effect of TFPI2 on TWIST1 expression was determined in breast cancer." (PMID 32248791, 2020). "The downstream signaling pathway involved in TFPI2/TWIST1/integrin α5 axis in breast cancer progression should also be investigated in the future study." (PMID 32248791, 2020). "The in vivo xenograft model was conducted via inoculation of Ad-pcDNA 3.1-TFPI2 into nude mice to investigate clinical application of TFPI2 in breast cancer." (PMID 32248791, 2020). "Gain-of functional assays were conducted via transfection of pcDNA 3.1-TFPI2 into MDA-MB-453 cell to determine the effects of TFPI2 on breast cancer proliferation." (PMID 32248791, 2020). "Over-expression of TFPI2 inhibited cell viability, proliferation, migration and invasion of breast cancer cells." (PMID 32248791, 2020). "The results showed that the expression of TFPI2 in breast cancer was lower than in normal breast specimens." (PMID 32248791, 2020).
breast cancer (continued). "The unusual nuclear localization of TFPI-2 also have been described in mammary cancer, and it was suggested that it is responsible for modulation of the expression of MMP-2 by interacting with the Ap2-α transcription factor." (PMID 32559232, 2020). "We first investigated the expression level of TFPI2 in breast cancer, and the down-regulation of TFPI2 was regarded as the starting point to further discuss the function and mechanism of TFPI2 in the occurrence and development of breast cancer." (PMID 32248791, 2020). "They reported that TFPI2 was related to poor prognosis of breast cancer, suggesting the potential of TFPI2 as a prognostic biomarker for breast cancer." (PMID 32248791, 2020). "In conclusion, we demonstrated that TFPI-2 levels were upregulated by miR-494 in the breast cancer cell line MCF-7 most likely by an indirect regulation involving the association between miR-494 and the transcription factors AHR and ELF-1." (PMID 32132611, 2020). "The present study showed that TWIST1 was negatively correlated with TFPI2 in breast cancer patients, and the inhibition ability of TFPI2 on breast cancer progression was reversed by over-expression of TWIST1." (PMID 32248791, 2020). "CCK8 and colony formation assay results indicated that over-expression of TFPI2 deceased cell viability and inhibited cell proliferation of MDA-MB-453 cells, suggesting the anti-proliferative ability of TFPI2 on breast cancer." (PMID 32248791, 2020). "Functional assays indicated that the inhibition abilities of TFPI2 over-expression on breast cancer progression were reversed by TWIST1 over-expression." (PMID 32248791, 2020). "We found a positive correlation between miR-494 levels and TFPI-2 mRNA levels in tumors from breast cancer patients supporting a tumor suppressive role." (PMID 32132611, 2020). "Our results showed that TFPI2-mediated down-regulation of TWIST1 decreased integrin α5 thereby inhibiting breast cancer progression." (PMID 32248791, 2020). "Consistent with expression in breast cancer tissues, TFPI2 was also down-regulated in human breast cancer cell lines (MDA-MB-453, MDA-MB-468 and MCF7) compared to breast fibroblast cell line (CCD-1095Sk) and MCF10A." (PMID 32248791, 2020). "CCK8 and colony formation assays showed that the inhibition ability of TFPI2 on breast cancer cell proliferation was promoted by additional transfection of pcDNA 3.1-TWIST1." (PMID 32248791, 2020). "TFPI-2 has been shown to be involved in breast cancer pathogenesis by inhibiting extracellular matrix degradation, and low levels are associated with disease progression." (PMID 32132611, 2020). "In conclusion, our study has elucidated a novel biological mechanism by which TFPI-2 suppresses breast cancer cell proliferation and invasion." (PMID 29051606, 2017). "Our study provides initial evidence that, in addition to maintaining the integrity of ECM, TFPI-2 suppresses breast cancer cell invasion through the regulation of MMP-2 gene expression." (PMID 29051606, 2017). "With over-expression of TFPI-2 or after treatment with exogenous rTFPI-2, we demonstrated that breast cancer cells exhibited a reduced ability to invade." (PMID 29051606, 2017). "Higher expression of metalloproteinases (MMPs) has been shown in breast cancer cells, and a correlation of reduced TFPI-2 levels with increased expression of MMP-2 mRNA was reported in pancreatic cancers." (PMID 29051606, 2017). "We showed that, with either over-expression of TFPI-2 or after treatment with exogenous rTFPI-2, breast cancer cells exhibited reduced proliferation and invasion." (PMID 29051606, 2017). "In this study, we investigated the potential mechanism of TFPI-2 in the suppression of breast cancer growth and invasion." (PMID 29051606, 2017). "On the other hand, the down-modulated genes codify for proteins involved in cell migration and invasion (SNAI2 and B2M) as well as for proteins (TFPI2) with a tumor suppressor role in breast cancer." (PMID 24962430, 2014).
breast cancer (continued). "The mechanism underlying the effect of DNA methylation on the repression of TFPI-2 in breast cancer cell lines has been reported previously." (PMID 25179542, 2014). "Our data show that in both cell lines and primary breast cancers, there is an association between LCT13 and TFPI-2as expression that correlates with downregulation of TFPI-2." (PMID 23703216, 2013). "We found that breast cancer tissues tended to have weaker degree or less portion of TFPI-2-positive staining than benign breast tumor tissues." (PMID 23497249, 2013). "In a total of 118 patients with followed-up, we found that 91 cases with TFPI-2 positive breast cancer." (PMID 23497249, 2013). "In the TFPI-2 positive breast cancer group, we compared the mean-density, which represent the level of TFPI-2 protein, with the clinicopathologic features including many common predictors of survival." (PMID 23497249, 2013). "The purpose of this study is to evaluate the prognostic value of TFPI-2 expression in breast cancer patients through examining the correlation between TFPI-2 expression and breast cancer clinicopathologic features." (PMID 23497249, 2013). "In our present study, we further investigated the correlation between TFPI-2 expression and clinicopathologic features of breast cancer." (PMID 23497249, 2013). "Compared with TFPI-2-positive breast cancer patients, the TFPI-2-negative group had higher proportion of lymph node metastasis and poor differentiation in histology and more common vessel invasion." (PMID 23497249, 2013). "Recently, we show that TFPI-2 is down-regulated in highly invasive breast cancer cell lines due to hypermethylation of TFPI-2 promoter." (PMID 23497249, 2013). "To find out the critical region of TFPI-2 promoter in breast cancer cell lines, we constructed several deletion constructs (P-1436, P-1142, P-962, P-667, P-572, P-397 and P-144) and transiently transfected them into MCF-7 cell line." (PMID 18053161, 2007). "Here, we have investigated the mechanism of DNA methylation on the repression of TFPI-2 in breast cancer cell lines." (PMID 18053161, 2007). "On the basis of these findings, we conclude that the down regulation of TFPI-2 in highly metastasis breast cancer was due to the abnormal hypermethylation in CpG dinucleotides of KLF-6 binding site." (PMID 18053161, 2007). "Expression of TFPI-2 protein in human breast cancer cell lines with different metastasis potential was examined by western blotting." (PMID 18053161, 2007). "Another question needed to be addressed is why the SP1 binding site in TFPI-2 promoter remains unmethylated in high metastasis breast cancer cell." (PMID 18053161, 2007). "miR-494 increases TFPI2 mRNA in MCF7 breast cancer cells and suppresses ovarian cancer progression." (PMID 40361374, 2025). "TFPI2 suppresses breast cancer cell proliferation and invasion through regulation of ERK signaling." (PMID 40361374, 2025). "Thus, TFPI-2 mRNA levels in malignant breast tumors were found to be reduced compared to those in normal breast tissues." (PMID 39153052, 2024). "In vitro, TFPI-2 has been reported to suppress breast cancer (BC) cell proliferation and invasion." (PMID 39153052, 2024). "Low or absent TFPI-2 expression in breast cancer patients was associated with increased metastatic growth and angiogenesis and thus with advanced disease progression, recurrence, and poor survival outcome." (PMID 36900315, 2023). "However, since integrin α5 and integrin β1 served as important mesenchymal marker to regulate EMT during breast cancer, the effect of TFPI2-mediated TWIST1 on regulation of integrin β1 also needs to be further investigated." (PMID 32248791, 2020). "TFPI-2 has been shown to be involved in breast cancer pathogenesis." (PMID 32132611, 2020). "In addition, a positive correlation between miR-494 and TFPI-2 mRNA expression levels in a clinical breast cancer material was demonstrated." (PMID 32132611, 2020).